C1QBP (complement C1q binding protein)
Diseases named in the same sentence as C1QBP in open-access papers (continued):
Sharing a sentence is not in itself a finding about the gene and the disease.
tumor (continued). "qPCR validated the higher mRNA expression levels of C1QBP and PFKP in tumor tissues." (PMID 41041346, 2025). "Although tremendous efforts have been made to induce crucial protein degradation in several tumours, no effective way has been established to clinically target C1QBP degradation in LSCC." (PMID 35366893, 2022). "We have clarified that C1QBP promotes RCC cell hypoxanthine catabolism via up-regulating XDH, and apoptosis by modulating XDH mediated ROS generation and pro-apoptotic proteins caspase-3 and bax/bcl2, then affects tumor progression." (PMID 35693733, 2022). "Unexpectedly, C1qbp mRNA expression was not affected by tumor stage or grade in analyzed CRC patient samples." (PMID 33102234, 2020). "Relative expression levels of C1QBP were analyzed using the Oncomine, Gene Expression Across Normal and Tumor Tissue (GENT), and The Cancer Genome Atlas (TCGA) databases." (PMID 30991713, 2019). "Additionally, analysis of OSCC xenograft tumor tissue in nude mice revealed that PA28γ’s regulation of C1QBP in OSCC cells is independent of the immune system." (PMID 40736231, 2025). "Additionally, our analysis of public single-cell sequencing data revealed that C1qbp-positive TAMs exhibit more immunosuppressive interactions with tumor cells compared to C1qbp-negative TAMs in TNBC patients, including CD47-SIRPα." (PMID 38773982, 2024). "Additionally, our FACS analysis showed that the membrane-bound form of C1qbp was primarily present in macrophages, rather than tumor cells, within the microenvironment of 4T1 tumors." (PMID 38773982, 2024). "However, whether C1QBP functions in TNBC cells under hypoxic conditions and mediates tumor-cell sensitivity to chemotherapy needs to be further investigated." (PMID 33708767, 2021). "The function of C1QBP is still unclear but it appears to play a role in tumorigenesis, although whether this role is tumorigenic or tumor suppressive is not clearly defined." (PMID 26999212, 2016). "Intriguingly, we found that the membrane form of C1qbp was only present in CD45-positive cells, not in tumor cells, and was predominantly distributed on macrophages." (PMID 38773982, 2024). "Here, in contrast to healthy colonic tissue protein expression of gC1qR negatively correlated with the mitochondrial marker TOM22 and was highest in grade 4 (G4) and lowest in grade 1 (G1) CRC, although C1qbp mRNA expression did not correlate with tumor stage and grade." (PMID 33102234, 2020).
cancer (68 papers, 2007 to 2025). A tumor composed of atypical neoplastic, often pleomorphic cells that invade other tissues. "A plethora of studies on the gain and/or loss of function have shown that p32/C1QBP is involved in promoting several malignancy traits in different cancer types." (PMID 38473963, 2024). "Previous studies have suggested that C1QBP acts as a diagnostic marker in cancer patients and is related to metastasis, progression, and poor OS." (PMID 39284282, 2024). "Elevated C1QBP expression has been linked to poor prognosis in several cancers, due to its role in promoting cell proliferation and metastasis by modulating mitochondrial function." (PMID 39596229, 2024). "In the last part of this study, we checked the association between C1QBP and immune cell infiltration, as the dysregulation of immune-suppression or immune cells infiltration results in cancer progression." (PMID 35711850, 2022). "p32, also known as p33/C1QBP, is a ubiquitous anionic cellular protein of 33 kDa implicated in various pathophysiological conditions including inflammation and cancer." (PMID 34711805, 2021). "C1q also has anti-cancer effects through immunosurveillance, Antigen-presenting cancer-associated fibroblasts (apCAFs) in lung malignancies produce C1q, which binds to T cells C1qbp to inhibit T cell apoptosis and promote tumor killing by immune cells." (PMID 37033981, 2023). "As conveyed by these results, C1QBP could be associated with certain key pathways related to post-transcriptional control and mitochondrial function in cancer progression." (PMID 30991713, 2019). "Our findings demonstrate that the targeting of C1QBP by PDBAG1 leads to mitochondrial destruction, induction of homologous‐recombination deficiency, and sensitisation of TNBC cancer cells with non‐BRCA mutations to PARPis." (PMID 39748215, 2025). "As Lyp‐1 (CGNKRTRGC) has been isolated through phage display screening and demonstrated its ability to bind C1QBP at the cell surface, it has gained significant value in various types of cancer research." (PMID 39748215, 2025). "Future studies should investigate the role of C1QBP in other cancer types and examine its interactions with additional DDR pathways." (PMID 40429658, 2025). "To assess the role of Vtn-C1qbp signaling in regulating the macrophage-mediated immune response to cancer, we examined the expression of C1qbp in immune cells." (PMID 38773982, 2024). "C1QBP has been shown to play a role in cell metabolism and immune evasion, which are critical factors in cancer cell survival and proliferation." (PMID 39596229, 2024). "This inhibitor was shown to mimic the effects of knocking down C1QBP in glioma cells and have an antiproliferative effect on this cancer cell model." (PMID 38473963, 2024). "Complement component 1, q subcomponent-binding protein mitochondrial (C1QBP)—in all carcinoma groups, the downregulation was significantly decreased." (PMID 39000458, 2024). "In cancer cells, the interaction between complement component 1q subcomponent binding protein (C1QBP) and APOA leads to the binding of C1QBP to APOA, inhibiting its expression and weakening APOA’s antioxidation ability, leading to carcinogenesis." (PMID 38067270, 2023). "In this current review, we summarize the current knowledge of the mechanism of C1QBP regulation of cancer and immunity." (PMID 36467687, 2022). "It has also been shown that C1QBP is activated by phosphorylation and is involved in cancer progression." (PMID 36012324, 2022). "C1QBP expression increases in multiple cancer cells in human, including breast, endometrial, ovarian, prostate, melanoma, lung, and colon cancer." (PMID 35310974, 2022). "In other words, C1QBP is involved in mitochondrial metabolism and plays an integral role in Myc-induced glutamine addiction in cancer cells." (PMID 36467687, 2022). "Based on the results from TNMplot and TIMER databases, we found that C1QBP was generally higher expressed in most of the cancer types including HCC." (PMID 35711850, 2022).
cancer (continued). "Due to its fundamental role in balancing OXPHOS and glycolysis, c1qbp−/− mice display embryonic lethality, while gC1qR is excessively up-regulated in cancer." (PMID 33102234, 2020). "Higher expression of C1QBP has been related to poorer clinical outcomes in breast, ovarian, endometrial, and cervical cancers." (PMID 30991713, 2019). "Sixty-seven differently expressed genes (DEGs) were commonly upregulated with C1QBP in five selected cancers derived from the Venn diagram, while only one DEG was commonly downregulated." (PMID 30991713, 2019). "We also investigated the genes usually co-altered with C1QBP with respect to the five cancer types with high C1QBP expression." (PMID 30991713, 2019). "Our study uncovers the importance of C1QBP expression and possible C1QBP-related pathways in cancer progression." (PMID 30991713, 2019). "The average expression of C1QBP was higher in cancer tissues than in the normal tissues in the analysis using the GENT database." (PMID 30991713, 2019). "Thus, these analyses might reveal the value of C1QBP expression for patient survival and provide a realization of the possible underlying mechanism of human cancers, which might bear a potential implication in C1QBP-targeted cancer therapy." (PMID 30991713, 2019). "In this systematic analysis of C1QBP expression in cancer databases, we provide evidence of the relationship between the altered expression of C1QBP and clinical outcomes." (PMID 30991713, 2019). "Beside five types of cancers, we analyzed C1QBP expression and its relevance in clinical outcomes in other cancers." (PMID 30991713, 2019). "In this current study, we systematically analyzed C1QBP expression in various cancers by utilizing online expression databases and bioinformatics tools." (PMID 30991713, 2019). "Differences of C1QBP mRNA expression between cancers and their counterparts were varied with cancer types." (PMID 30991713, 2019). "To examine the differential expression level of C1QBP in various cancers and their counterparts, we utilized the Oncomine and GENT databases." (PMID 30991713, 2019). "Analysis of datasets revealed that C1QBP expression is significantly augmented in various cancer cells, compared to their normal counterparts." (PMID 30991713, 2019). "Our study provides a systematic analysis suggesting C1QBP as a cancer target in various types of cancers." (PMID 30991713, 2019). "C1qBP is also involved in cell proliferation, migration and apoptosis, and has been reported to be upregulated in many human cancers." (PMID 27812893, 2017). "Serum complement C1q participates in cancer suppression via interaction with C1qBP and downstream WWOX." (PMID 25779665, 2015). "Such research could provide further insights into the broader implications of C1QBP in radiation responses and its viability as a universal target in cancer therapy." (PMID 40429658, 2025). "Consequently, C1QBP emerges as a paramount factor influencing cancer drug resistance and potentially regulating macrophage polarization, representing dual elements in OS progression." (PMID 39553438, 2024). "The findings suggest the possibility that cellular signalling pathways mediated by C1QBP may also differ depending on the organ of origin of the cancer." (PMID 36674861, 2023). "C1QBP was found to be closely related to tumorigenesis or metastasis of various cancers." (PMID 35493104, 2022). "To this end, we started to check C1QBP levels in a pan-cancer manner." (PMID 35711850, 2022). "The phosphorylation-induced activation of C1QBP by HASPIN in cancer cells may be involved in the growth of cancer cells." (PMID 36012324, 2022). "Thus, the lack of the N-terminus in the cMDT for Bladder-TCC and Uterus-AdenoCA points towards an oncogenic role of C1QBP outside the mitochondria in both cancer types." (PMID 32879328, 2020). "Increased expression of C1QBP promotes the oxidative phosphorylation in cancers." (PMID 30991713, 2019).
cancer (continued). "Similarly, our analysis revealed that C1QBP expression is significantly higher in most types of cancer cells compared to their normal counterparts, and is negatively correlated with patient survival." (PMID 30991713, 2019). "In these cancers, expression of C1QBP may play as a prognostic marker for the cancer progression which yet to be further validated by additional studies." (PMID 30991713, 2019). "Finally, we aimed to find the potential signaling mechanism involved with C1QBP expression in cancers." (PMID 30991713, 2019). "Additionally, the relative expression of C1QBP in other cancers, and correlation of C1QBP expression with patient survival were investigated." (PMID 30991713, 2019). "Mutations and copy number alterations in C1QBP were also analyzed using cBioPortal, and subsequently, the relationship between C1QBP expression and survival probability of cancer patients was explored using the PrognoScan database and the R2: Kaplan Meier Scanner." (PMID 30991713, 2019). "This consistent trend in C1QBP expression in cancers suggests a commonality among different cancer types, where C1QBP-related molecular pathways may be functional." (PMID 30991713, 2019). "Therefore, PA28γ and C1QBP are potential targets for the treatment and prognosis of cancer." (PMID 40736231, 2025). "However, the role of the membrane form of C1qbp in cancer development has seldomly been reported." (PMID 38773982, 2024). "Therefore, our analysis may provide valuable insights into C1QBP as a potential therapeutic target for various human cancers." (PMID 30991713, 2019). "Several authors have demonstrated in various cancer types that C1QBP can positively regulate the autophosphorylation of different RTKs such as EGFR, VEGFR, and IGFR in various cancer types by binding to lipid rafts containing these receptors." (PMID 38473963, 2024). "The gC1qR protein, referred to as P32/C1qBP/HABP1, is a versatile protein that is found at elevated levels in various types of cancer and possesses prognostic significance." (PMID 39629004, 2024). "Significant differences were observed in the protein concentration levels of S100P, PIGR, C1QBP, TAGLN, and CNN1 between cancer and inflammatory lesions (P ═ 0.0006, P ═ 0.0032, P ═ 0.0008, P < 0.0001, P ═ 0.0094, respectively)." (PMID 39284282, 2024). "Significant differences were observed in protein concentration levels between cancer and inflammatory lesions for S100P, PIGR, C1QBP, TAGLN, and CNN1 (P ═ 0.0006, P ═ 0.0032, P ═ 0.0008, P < 0.0001, P ═ 0.0094, respectively) as shown in." (PMID 39284282, 2024). "For example, several proteins were pan-cancer markers present in EVs from nearly all PDX models, including ALB, C1QBP, CDH1, and PKM." (PMID 36470535, 2023). "gC1qR, also named P32/C1qBP/HABP1, is a multifunctional protein that is overexpressed in various cancers and holds prognostic value." (PMID 36776869, 2023). "In the Intrinsic Pathway for Apoptosis, enriched genes such as complement C1q binding protein (C1QBP), also referred to as p32, are expressed in various cancer types." (PMID 33892676, 2021). "Here, mice receiving Zfra4-10 or WWOX7-21 peptide alone exhibited an increased binding of endogenous tumor suppressor WWOX with ERK, C1qBP, NF-κB, Iba1, p21, CD133, JNK1, COX2, Oct4, and GFAP in the spleen, brain, and/or lung which led to cancer suppression." (PMID 32764489, 2020).
cancer (continued). "Since cell motility is an essential part of cancer metastasis, we performed a transwell assay in 786-0 and highly metastatic ACHN cells with different expressions of C1QBP." (PMID 28428626, 2017). "C1QBP, a member of the FAM gene family, can regulate mitochondrial activity, affecting both tumors and immune cells, which has significant implications for cancer treatment." (PMID 39553438, 2024). "C1QBP is reported to exert pleiotropic effects on many cellular processes, including mitochondrial homeostasis, mitochondrial oxidative phosphorylation (OXPHOS) and in nucleus–mitochondrial interactions, inflammation, and cancer." (PMID 35310974, 2022). "C1QBP stabilizes the MRE11 protein by forming an MRC complex with MRE11/RAD50 and inhibiting MRE11 exonuclease activity, thereby demonstrating that C1QBP plays a crucial role in the DNA damage response and serves as a potential target for cancer therapeutics." (PMID 33708767, 2021). "Additionally, Zfra4-10 or WWOX7-21 peptide increases the complex formation of WWOX with C1qBP, CD133, p21, JNK1, COX2, and p-ERK in the spleen, which correlates with cancer suppression in vivo." (PMID 32764489, 2020). "Both C1qBP and COX2 are involved in cancer growth, progression, and inflammation." (PMID 32764489, 2020). "Notably, Zfra4-10 or WWOX7-21 peptide induced the binding of endogenous WWOX with ERK, C1qBP, NF-κB, Iba1, p21, CD133, JNK1, COX2, Oct4, and GFAP in the spleen, brain, and/or lung, which correlates with cancer suppression." (PMID 32764489, 2020). "The correlation of C1QBP expression with patient survival and molecular function of C1QBP in relation to cancer progression has not been comprehensively studied." (PMID 30991713, 2019). "Moreover, C1QBP, BCAP31 and PTMS protein were predicted as their interactor pathways in cancer." (PMID 32025240, 2020). "Additionally, suppression of C1QBP by HPV type 16, dramatically induced cancer cell immune evasion." (PMID 32025240, 2020). "There was no downregulated expression of C1QBP in all types of cancers in this analysis." (PMID 30991713, 2019).